CDK4 (cyclin dependent kinase 4)
Diseases named in the same sentence as CDK4 in open-access papers (continued):
Sharing a sentence is not in itself a finding about the gene and the disease.
tumor (continued). "CDK4/6 inhibitors can block the cycle of tumor cells and inhibit their proliferation and growth." (PMID 37305685, 2023). "Emerging preclinical studies revealed diverse immunomodulatory effects of CDK4/6 inhibition, such as an enhanced immune infiltration into the tumor microenvironment, elevated antigen presentation and modulation of the cytokine milieu, supporting antitumor immune response." (PMID 36817127, 2023). "These micro-architectural changes in the tumor might precede changes in radiographic features during CDK4/6i treatment." (PMID 37567880, 2023). "Inhibition of CDK4/6 in vivo has been shown to inhibit cyclin D‐CdK4‐mediated Spoz protein phosphorylation, thereby increasing PD‐L1 protein levels, and this can increase the number of tumor infiltrating lymphocytes and enhance tumor immunity." (PMID 37143582, 2023). "Targeting CDK4/6 can also prevent their cell cycle-independent tumor-promoting activities." (PMID 36768557, 2023). "Interrupting the "YB-1-PARP1" loop enhanced the tumor-killing effects of CDK4/6i." (PMID 38037159, 2023). "In a study published by Mangiola and colleagues, several tumor‐associated alterations were present in brain adjacent to the tumor area, as well as in the TC: del(1p36), del(2p21), MDM2 and CDK4 amplification, amplification of 15q24.1, chromosome 19 and 22 losses." (PMID 36300592, 2023). "After four weeks, both single treatments by GAA or CDK4/6 inhibitor ribociclib only partially delayed the growth of subcutaneous tumors, while the combination of the two drugs almost completely inhibited the tumor proliferation." (PMID 37452037, 2023). "We investigated whether MKShi/ERSlo tumours displayed molecular features predictive of response to CDK4/6i therapy." (PMID 37935787, 2023). "The results showed that Cdk4−/− tumor cells underwent more DNA damage than control cells." (PMID 37833461, 2023). "Furthermore, mTOR inhibitors in combination with CDK4/6 inhibitors resulted in a greater reduction of cell proliferation and tumor growth." (PMID 36792625, 2023). "The results showed that co-inhibition of CDK4/6 and PD-1 displayed enhanced tumor control." (PMID 36871040, 2023). "In addition, our data support that when CDK4/6 inhibition is discontinued, palbociclib-insensitive tumour growth is initiated." (PMID 37190140, 2023). "CDK4/6 inhibition provides new hope for HPV-negative tumor patients." (PMID 36646686, 2023). "A growing body of research suggests that loss of the retinoblastoma tumor suppressor gene (Rb), leads to accelerated angiogenesis and tumor progression which is one of the most important biomarkers associated with acquired resistance and lower PFS to CDK4/6i32,33." (PMID 37567880, 2023). "The identification of the CCNI–CDK6 complex may enable a better understanding of the tumor genetic landscape that determines sensitivity to CDK4/6 inhibition." (PMID 37081792, 2023). "In addition, gene set enrichment analysis (GSEA) showed enrichment of signatures associated with “Type I interferon response” and “Interferon-g (IFN-γ) response” in Cdk4−/− tumor tissues versus control tumor tissues." (PMID 37833461, 2023). "Additionally, the impact of the tumor microenvironment, including immune cells and stromal components, on CDK4/6 inhibitor response and resistance requires further exploration." (PMID 37511548, 2023). "Several in vitro studies have shown that CDK4/6 inhibition modulates immune responses and may cooperate with ICIs to suppress tumor growth." (PMID 37298520, 2023). "Indeed, recent studies in ER-positive breast cancer models demonstrated that low doses of novel FOXM1 inhibitors acted synergistically with low doses of CDK4/6 inhibitors (abemaciclib, palbociclib, or ribociclib) to efficiently suppress tumor cell growth." (PMID 37686402, 2023). "With the high abundance of Cyclin D1 and CDK4/6, cells could escape from critical cell checkpoints, then grow out of control and develop into malignant tumor cells." (PMID 37814227, 2023).
tumor (continued). "Most ATC and PDTC patients could at least initially respond to CDK4/6i, which may arrest tumor growth, facilitating surgery in the neo-adjuvant setting or improving the efficacy of other treatment option." (PMID 37964967, 2023). "However, emerging evidence suggests that AURKA also mediates resistance to CDK4/6 inhibitors in vitro and in tumor samples." (PMID 37760421, 2023). "Recently, studies have indicated that CDK4/6 inhibitors may regulate the expression of PD‐L1 in tumour cells." (PMID 36127291, 2023). "Lastly, CDK4/6 inhibition was shown to upregulate programmed death-ligand 1 (PD-L1) in tumor cells." (PMID 37835528, 2023). "In a recent whole-exome sequencing (WES) study, alterations in numerous genes including AKT1 and ERBB2, RAS pathway activating alterations, AURKA and CCNE2 amplification, and FGFR2 alterations were identified in tumor biopsies from patients with intrinsic or acquired CDK4/6i resistance." (PMID 37475004, 2023). "Moreover, like CDK2, CDK4/CDK6 exert oncogenic roles in this tumor type, especially in MYC-amplified forms." (PMID 36839989, 2023). "As a result, this study provided an alternative synergistic way to boost tumor photoimmunotherapy in conjunction with Cdk4 inhibition, which could effectively reduce tumor growth with negligible toxicity." (PMID 36987269, 2023). "In addition, more cleaved-caspase-3 positive cells were found in Cdk4−/− tumor tissues than control tumor tissues, indicating more tumor cells were undergoing apoptosis in Cdk4−/− tumors." (PMID 37833461, 2023). "In order to further explore whether the reduced tumor growth of Cdk4−/− cancer cells mainly relied on CD8+ T cells, an anti-CD8 antibody was injected by intravenous to deplete CD8+ T cells in C57BL/6 N mice." (PMID 37833461, 2023). "Indeed, elevated CDK4 expression is correlated with metastasis potential and poor prognosis in this tumor type." (PMID 36839989, 2023). "Additionally, in a xenograft model of HCC, the coadministration of the cyclin-dependent kinase 4/6 inhibitor palbociclib in combination with FGFR4-selective inhibitors facilitated tumor regression, which indicates a potential new strategy for HCC treatment." (PMID 36980566, 2023). "The results showed that immunization of mice with Cdk4−/− tumor cells could effectively suppress WT tumor growth on the right flank." (PMID 37833461, 2023). "Among the five tumor samples with no phosphorylated CDK4 (profile A), we identified two samples with mutated RB1 (a nonsense and a frameshift mutation)." (PMID 37964967, 2023). "Combination of CDK4/6 inhibition and PD-1 blockade significantly induced tumor cell death in vitro in MC38 murine-derived organoids, as evidenced by tumor live/dead staining as well as by T cell-mediated tumor growth inhibition in vivo in syngeneic MC38 and CT26 mouse models." (PMID 37114038, 2023). "However, the underlying mechanisms of CDK4 and CDK6 in cancer cells involved in regulating anti-tumor responses remain to be elucidated." (PMID 37833461, 2023). "However, the use of CDK4/6 inhibitors with immunotherapy targeting PD-1 receptors enhanced tumor regression and increased survival rates in mouse models of cancer." (PMID 38137564, 2023). "So the mechanisms of CDK4/6 in anti-tumor immunity studied with CDK4/6 inhibitors lack accuracy." (PMID 37833461, 2023). "In contrast, CDK4/6 inhibitors can contribute to the death of many tumor cells by promoting the apoptotic pathway and modulating the immune system to halt the progression of tumor development." (PMID 37305685, 2023). "In addition, CDK4/6i have been shown to increase tumor cell antigen presentation via upregulation of the major histocompatibility complex (MHC) class I, thereby enhancing cancer cell immunogenicity and recognition by the immune system." (PMID 37509319, 2023). "Next, we assessed the effect of palbociclib (an inhibitor of CDK4/6) on tumor cell growth in vitro." (PMID 37833461, 2023).
tumor (continued). "These new CDK4/6 inhibitors may have different selectivity profiles, mechanisms of action, and spectrums of activity, which may be beneficial in addressing tumor heterogeneity and acquired resistance." (PMID 37176102, 2023). "The treatment of PDAC PDTX models with MEK and CDK4/6 inhibitors was demonstrated to have a profound impact on the myeloid and T-cell populations within the tumor compartment, eliciting sensitivity to anti-PD1 (programmed cell death protein 1) therapy in immune-competent models." (PMID 36765923, 2023). "Similarly, studies in mice reported reduced tumor growth when cyclin-dependent kinase 4/6 (CDK4/6) drugs were administered in a time-dependent manner, showing higher efficacy in a morning dosing regimen compared to nighttime dosing." (PMID 36672355, 2023). "A targeted genomic analysis of 348 pretreatment tumors treated with CDK4/6i plus ET found loss-of-function mutations in FAT atypical cadherin 1 to be associated with much shortened PFS, although these mutations were only present in 1.7% of the tumor samples." (PMID 37475004, 2023). "Moreover, PI3K inhibitors in addition to CDK4/6 inhibitors and ET induced a tumor regression and one CR was also observed." (PMID 36900211, 2023). "Additionally, we focus on new experimental and clinical evidence that CDK4/6 inhibition promotes key facets of antitumor immunity in the tumour microenvironment, tipping the balance in favor of the induction of an effective antitumor immune response." (PMID 36768557, 2023). "We found that higher intratumoral Haralick entropy that captures tumor heterogeneity was associated with non-response to CDK4/6i/ET and poor OS." (PMID 37567880, 2023). "Together with previous results, we suggested that DNA damage caused by Cdk4-deficiency could activate cGAS-STING pathway, stimulate type I IFN and enhance anti-tumor immunity." (PMID 37833461, 2023). "It is known that CDK4/6i has direct effects on T lymphocytes, with the reduction in T regulatory cells and direct activation of effector T lymphocytes leading to a stronger anti-tumor immune response." (PMID 37509319, 2023). "Furthermore, immunofluorescence also showed that more CD8+ T cells were infiltrated in Cdk4−/− tumor tissues compared with vector group." (PMID 37833461, 2023). "Preliminary results from the TAPUR basket trial demonstrated the anti-tumor activity of palbociclib monotherapy in 29 patients with advanced STS with CDK4 amplification and no RB1 mutations (histologic subtype breakdown not reported)." (PMID 37298520, 2023). "CDK4/6 inhibition reduced abundance of MDSCs and TANs in tumor tissue, and the combined CDK4/6 inhibitors and PD-1 blockade therapy may impact dendritic cell infiltration and function in the process of antigen processing and presentation." (PMID 36871040, 2023). "Deletion of Cdk4 or Cdk6 in tumor cells significantly reduce tumor growth." (PMID 37833461, 2023). "Moreover, they demonstrated that targeting the p16-CDK4/6 interaction sensitizes p16-overexpressing tumor cells to CDK4/6is." (PMID 37833875, 2023). "In a recent study, a combination of CDK4/6 and mTOR inhibitors treatment showed a synergistic effect against iCCA tumor cell proliferation, but other CDK4/6 functions in transcription or differentiation independent of cell cycle processes reported recently remain." (PMID 36978140, 2023). "Recent studies suggested that CDK4/6is may also promote the cytotoxic T-cell-mediated clearance of tumor cells and a tumor-suppressive immune microenvironment." (PMID 36765923, 2023). "More clinical investigation will be needed to elucidate whether there is cancer-type selectivity for the beneficial anti-tumor efficacy from the combination of CDK4/6 inhibitor and ICI treatment." (PMID 37631380, 2023).
tumor (continued). "We therefore hypothesised that inhibiting CDK7, in combination with CDK4/6 inhibition with palbociclib, could target alternative pathways and prevent palbociclib-insensitive tumour growth." (PMID 37190140, 2023). "Nevertheless, there could be a strong rationale for combining anti-BRAF therapy with CDK4/6 inhibition, especially in neo-adjuvant settings, to improve the probability of effective tumor surgical resection." (PMID 37964967, 2023). "The role of CDK4/6 inhibitors in anti-tumor immunity has been corroborated by several studies." (PMID 37345111, 2023). "Moreover, CDK4/6 inhibitors enhance antitumor immunity through tumor infiltration and activation of T cells via transcriptional reprogramming." (PMID 36635767, 2023). "Whole-exome sequencing showed that this tumor also harbored CDK4, TSPAN31, and JUN amplification." (PMID 37881487, 2023). "We further investigated whether animals immunized with Cdk4−/− cancer cells could form an immunological memory to protect host from tumor growth of WT cancer cells." (PMID 37833461, 2023). "Since the primary function of CDK4/6, which is activated by the D-type cyclins D1, D2, and D3 (cyclin D), is to drive cell-cycle progression from G1 to S phase, it is believed that the major mechanism responsible for anti-tumor activity of CDK4/6 inhibitors is induction of cell cycle arrest." (PMID 37833461, 2023). "A recent study showed that the combined treatment with CDK4/6 inhibitor and andoncolytic virus-induced immunogenic cell death, enhanced antitumor immunity, inhibited tumor growth, and prolonged the survival of tumor-bearing mice." (PMID 36998447, 2023). "Because immune-checkpoint inhibitors have recently been developed, and their activity may be correlated with PD-L1 expression on tumour cells, they may be able to counteract the detrimental immune-suppressive effect of CDK4/6 inhibitors." (PMID 36768557, 2023). "At the same time, we stained cell cycle pathway-related molecules in tumor tissues, and the results showed that compared with the control groups, the staining of p21 and p27 was stronger, while the staining of CDK4 and CDK6 was weaker in the bortezomib-treated groups." (PMID 37864031, 2023). "In this study, we developed a new compound ZC-22, which can effectively inhibit the activity of both PARP and CDK4/6 and displayed better anti-tumor efficacy than PARPi Olaparib and CDK4/6i Abemaciclib monotherapy, or even combination therapy in both cell and mouse models." (PMID 35270034, 2022). "While we observed that FAK inhibition could reduce B16F10 tumor growth, it still remains to be seen if FAK-I-mediated loss of CDK4/6 protein increases PD-L1 expression in B16F10 cells and could eventually lead to escape from the immune system." (PMID 35525274, 2022). "Here, the authors show that p16 overexpression may be linked to reduced efficacy of CDK4/6 inhibition, and show that the combination with PI3K inhibitors may increase anti-tumour effects." (PMID 36071033, 2022). "In addition to the direct effect on cycling tumor cells, CDK4 influences the composition of cells in tumor microenvironment and inhibition of this pathway results in changes in the tumor-infiltrating immune cell populations." (PMID 35936751, 2022). "In particular, co-amplification of MDM2 and CDK4 is more prevalent in the low-grade parosteal OS (67%) compared to high-grade classical OS (12%), showing a correlation between amplification levels and tumor grading and progression in the former group." (PMID 35070121, 2022). "In addition, we found that the anti-tumor effect is mediated through modulation of the CDK4/Cyclin D/RB/E2F and Caspase/Bcl-2 signal pathways." (PMID 35686110, 2022). "Furthermore, combining CDK4/6i with BRAFi and MEKi in vivo enhanced anti-tumor responses mediated by adoptive T-cell transfer." (PMID 35513054, 2022).
tumor (continued). "Our study supports the clinical development of therapeutic strategies co-targeting ER, CDK4/6 and CDK2 following progression on AI-monotherapy or combined CDK4/6i and ET to improve survival of patients exhibiting high tumor levels of CDK6, p-CDK2, and/or cyclin E1." (PMID 36153348, 2022). "Developing small inhibitors based on CDK4/CDK6 is an alternative approach in tumor treatment." (PMID 36376832, 2022). "The signaling of GSK-3, PTPN2, SHP2, and CDK4/6 all decrease PD-L1 expression on tumor cells." (PMID 35911672, 2022). "Preclinical and clinical evidence suggests that CDK4/6 inhibitors might be utilized alone or in combination with other chemotherapy or targeted treatments in various tumor situations." (PMID 35530846, 2022). "CDK4/6 inhibitor inhibits tumor growth in xenograft mouse model." (PMID 35880418, 2022). "Moreover, in a syngeneic murine model of TNBC, combined inhibition of both PI3K and CDK4/6 induced increased activation of tumor-infiltrating T-cells, also suggesting an immunogenic effect." (PMID 35712501, 2022). "Many clinical trials of CDK4/6i in several tumor types have achieved promising results." (PMID 35686110, 2022). "Firstly, it suggests that tumour cells with ongoing replication stress may be more sensitive to the long‐term effects of CDK4/6 inhibition." (PMID 35037284, 2022). "In theory, CDK4/6i could be combined with cytotoxic agents that target the S or M phase of the cell cycle to kill tumor cells." (PMID 35686110, 2022). "To determine whether induction of normal cells into senescence upon treatment with CDK4/6i happens in vivo, we exposed mice to a clinically relevant and tumor‐suppressive dose of abemaciclib." (PMID 34985783, 2022). "Thus, we sought to understand how high levels of CDK4 and filamin A specifically sensitize tumour cells to paclitaxel." (PMID 36477027, 2022). "It forms a complex with CDK4/6 to promote the phosphorylation of retinoblastoma (RB) gene, which leads to unrestrained E2F transcription factors and promotes cell cycle progression and the malignant proliferation of tumor cells." (PMID 35463335, 2022). "We next sought to examine whether these results were broadly applicable to tumour types that are known to be responsive to CDK4/6 inhibitor treatment." (PMID 35037284, 2022). "In addition, we demonstrated that LPM3770277 had significant anti-tumor efficacy in vivo in mouse xenograft tumor models, and its hematological toxicity was much lower than that of CDK4/6 inhibitor abemaciclib." (PMID 35479314, 2022). "Moreover, it produces tumor regression when co-administered with either CDK4/6 inhibitors or hormonal therapy in xenografts models of HER2 cancer." (PMID 36139701, 2022). "Our data also showed that co-targeting FGFR4 and CDK4/6 could significantly inhibit tumor growth in both the mouse models." (PMID 35463335, 2022). "In total, between 20.0% and 23.3% of the tumours are Rbpositive/p16negative, Rbpositive/CDK4positive, or Rbpositive/CDK6high, which corresponds to the group of patients that might benefit from CDK4/CDK6 inhibitor treatment." (PMID 34921235, 2022). "In addition to immunomodulation through tumor-intrinsic mechanisms, CDK4/6i also modulates anti-tumor immunity through direct effects on T lymphocytes." (PMID 35444175, 2022). "CDK4/6 inhibitors can stop tumor cells from progressing from S to G phase, halting tumor growth." (PMID 35433677, 2022). "CDK4/6i can also increase PD-L1 expression in tumor cells in vivo." (PMID 35513054, 2022). "Therefore, in recent years, in the research and development of anti-tumor drugs, CDK4/6 has become a hot spot to achieve the purpose of anti-tumor by regulating the protein expression level in the signaling pathway." (PMID 36091173, 2022).